SIX1 (SIX homeobox 1)
Diseases named in the same sentence as SIX1 in open-access papers (continued):
Sharing a sentence is not in itself a finding about the gene and the disease.
Wilms tumor (continued). "In addition to a site bound only by SIX1-Q177R, Wilms tumor ChIP-seq peaks containing SIX1/SIX1-Q177R motifs bound by both SIX1 and SIX1-Q177R, were identified at proximal and distal regions near the WNT5A locus." (PMID 37815464, 2023). "Utilizing multiple Wilms tumor transcriptomic datasets, we identified upregulation of the gene encoding non-canonical WNT ligand WNT5A in addition to other WNT pathway effectors in SIX1/2-Q177R mutant tumors." (PMID 37815464, 2023). "However, immunohistochemical studies of Wilms tumors have demonstrated localization of both SIX1 and NCAM in all histological compartments." (PMID 37815464, 2023). "To identify putative target genes of SIX1-Q177R in Wilms tumor and characterize these as either tumor-specific or conserved normal kidney regulatory targets, we integrated three SIX1 ChIP-seq peak sets from SIX1 tumor, SIX1-Q177R tumor and from hFK." (PMID 37815464, 2023). "Putative target genes in Wilms tumor were compared to the top 500 target genes of SIX1 in hFK." (PMID 37815464, 2023). "SIX1 alone has been shown to be overexpressed in many forms of cancer such as breast, ovarian, cervical, Wilms tumor, osteosarcoma, rhabdomyosarcoma, and several others." (PMID 34490256, 2021). "This analysis demonstrates that both SIX1 and SIX1-Q177R recapitulate key NPC regulatory activities that could contribute to the persistence of NPC-like characteristics in Wilms tumor, and that SIX1-Q177R is a candidate for regulation of several differentially expressed genes in SIX1/2-Q177R tumors." (PMID 37815464, 2023). "Furthermore, SIX1 protein expression was shown in the blastemal elements of Wilms tumors." (PMID 27213811, 2016). "Genes identified as targets of wild-type SIX1 in both Wilms tumor and hFK but not of SIX1-Q177R include established NPC-enriched genes FOXC1 and TMEM100, both of which were also found to be upregulated in SIX1/2-Q177R tumors." (PMID 37815464, 2023). "In agreement with the Wilms tumor ChIP-seq data, these PBM and EMSA data also demonstrated that both proteins can bind the other's preferred motif both in vitro and in vivo, although our EMSA data suggest that SIX1-Q177R binds the SIX1-preferred motif with similar affinity to that of SIX1." (PMID 37815464, 2023). "Despite the evidence presented here for enhanced binding affinity of SIX1-Q177R and significant association of this mutation with the upregulation of WNT signaling pathway effector genes, SIX1/2-Q177R is unlikely to be solely responsible for this DGE in Wilms tumors." (PMID 37815464, 2023). "While we do not directly compare the magnitude of WNT5A expression in Wilms tumors to that in hFK, the results of our DGE analysis appear to generally agree with the findings by Tamimi and colleagues, except in the case of SIX1/2-Q177R tumors." (PMID 37815464, 2023).
gastric cancer (14 papers, 2017 to 2023). A primary or metastatic malignant neoplasm involving the stomach. "Collectively, our data show that circNHSL1 acts as an oncogenic gene in gastric cancer progression through miR-1306-3p/SIX1/Vimentin axis, and may serve as a novel diagnostic marker and target for treatment of gastric cancer patients." (PMID 31438963, 2019). "CircNHSL1 promotes gastric cancer progression through miR-1306-3p/SIX1/Vimentin axis, and may serve as a novel diagnostic marker and target for treatment of gastric cancer patients." (PMID 31438963, 2019). "Meanwhile, SIX1 directly binds to vimentin promoter to further enhance vimentin expression This result suggested that CircNHSL1 promoted gastric cancer progression through the miR-1306-3p/SIX1/Vimentin axis." (PMID 36750914, 2023). "Mechanistically, circNHSL1 promoted gastric cancer invasion and metastasis by acting as a miR-1306-3p sponge to derepress its target SIX1." (PMID 36750914, 2023). "SIX1 regulation of Cyclin D1 implies that Cyclin D1 is at the crossroads of multiple cellular signaling pathways involved in the progression of gastric cancer." (PMID 36769170, 2023). "Results indicated that sf-RON regulated the cell proliferation and glucose metabolism of gastric cancer by participating in a sf-RON/β-catenin/SIX1 signaling axis and had significant implications for choosing the therapeutic target of gastric cancer." (PMID 32399910, 2021). "For example, circNHSL1 was reported to promote gastric cancer progression through acting as a miR-1306-3p sponge to relieve the repressive effect of miR-1306-3p on its target SIX1." (PMID 32299063, 2020). "SIX1 promotes proliferation, migration, invasion, and metastasis of multiple cancer cells, such as breast, liver, and gastric cancer cells." (PMID 32258386, 2020). "In gastric cancer cells, SIX1 inhibits the mitochondrial apoptosis pathway via caspase-7, and it regulates proliferation and invasion by targeting the ERK pathway." (PMID 32258386, 2020). "A series of molecular experiments demonstrated that circNHSL1 promotes SIX1 expression in gastric cancer." (PMID 31438963, 2019). "We analyzed the level of circNHSL1 and SIX1 in 61 paired gastric cancer tissues among above 93 paired gastric cancer tissues, and found that the level of circNHSL1 positively correlated with the level of SIX1 (p < 0.01)." (PMID 31438963, 2019). "In summary, circNHSL1 promotes malignance of gastric cancer cells through enhancing SIX1 expression." (PMID 31438963, 2019). "Pearson correlation analysis indicated that miR-1306-3p ISH score negatively correlated with SIX1 IHC score in both gastric cancer tissues and normal gastric tissues." (PMID 31438963, 2019). "Given the roles of circNHSL1 and SIX1 on promoting gastric cancer progression, we detected the role of miR-1306-3p on the migration and invasion of gastric cancer cells." (PMID 31438963, 2019). "To summary, SIX1 promotes gastric cancer progression by positively regulating Vimentin expression in the transcriptional level." (PMID 31438963, 2019). "Pearson correlation analysis showed that the mRNA expression level of SIX1 was positively correlated with that of Vimentin in above 61 paired gastric cancer tissues (p < 0.05)." (PMID 31438963, 2019). "We detected that SIX1 is up-regulated in gastric cancer tissues, and promotes the mobility, migration and invasion of gastric cancer cells." (PMID 31438963, 2019). "The results illustrated that SIX1 promoted cell mobility, migration and invasion of gastric cancer cells." (PMID 31438963, 2019). "We analyzed the expression of miR-1306-3p and SIX1 in above 61 paired gastric cancer tissues, and found SIX1 was up-regulated in 77.05% (47/61) gastric cancer tissues and the level of miR-1306-3p negatively correlated with the level of SIX1." (PMID 31438963, 2019). "Functionally, SIX1 reversed the ability of miR-1306-3p to inhibit the mobility, migration and invasion of gastric cancer cells." (PMID 31438963, 2019).
gastric cancer (continued). "Combining previous results, we demonstrate that circNHSL1 promotes gastric cancer progression through serving as a miR-1306-3p sponge and relieving its suppression on target gene SIX1 expression." (PMID 31438963, 2019). "A recent report showed that Six 1 inhibits mitochondrial apoptosis pathway via caspase-7 in gastric cancer cells, suggesting a potential link between Six1 and mitochondrial function in human cancers." (PMID 29113360, 2017). "that CircNHSL1/miR-1306-3p/SIX1 axis could affect the development and progression of gastric cancer by cooperating with Vimentin and EMT." (PMID 33726765, 2021). "For example, circNHSL1 served as an oncogenic circRNA in progression and metastasis of gastric cancer through the circNHSL1/miR-1306-3p/SIX1/Vimentin regulatory gene network; circDONSON promoted progression and development of GC cells via the NURF complex-dependent activation of SOX4 signaling." (PMID 32386516, 2020). "Importantly, circNHSL1 promoted invasion and metastasis of gastric cancer by acting as a miR-1306-3p sponge to relieve its repression on target SIX1." (PMID 31438963, 2019). "To summary, miR-1306-3p suppresses gastric cancer progression through inhibiting SIX1 expression." (PMID 31438963, 2019). "Furthermore, miR-1306-3p reversed the ability of circNHSL1 to enhance mRNA and protein expression of SIX1 and Vimentin in gastric cancer cells." (PMID 31438963, 2019). "Taken together, circNHSL1 promotes gastric cancer progression by miR-1306-3p/SIX1/Vimentin axis." (PMID 31438963, 2019). "Taken together, circNHSL1 promotes gastric cancer progression via SIX1." (PMID 31438963, 2019). "Then, we tested the functions of SIX1 in gastric cancer cells." (PMID 31438963, 2019). "Furthermore, we demonstrated that circNHSL1 promotes invasion and metastasis of gastric cancer cells in vitro and in vivo by targeting the miR-1306-3p/SIX1/Vimentin axis." (PMID 31438963, 2019). "Furthermore, down-regulation or up-regulation of circNHSL1 decreased or increased SIX1 protein expression in gastric cancer cells, respectively." (PMID 31438963, 2019). "Finally, we identify a sf-RON/β-catenin/SIX1 signaling axis in gastric cancer." (PMID 32399910, 2021). "However, little is known about the functions and regulatory mechanisms of SIX1 in gastric cancer." (PMID 31438963, 2019). "Nevertheless, the detail functions and mechanisms of SIX1 in gastric cancer remain unknown." (PMID 31438963, 2019). "Furthermore, SIX1 contributed to the proliferation, invasion, and EMT of gastric cancer cells via multiple pathways, including cyclin D1, ERK, MMP-2, and E-cadherin." (PMID 36750914, 2023). "Another oncogene named Sine oculis homeobox homolog 1 (SIX1) is involved in positively regulating the expression of Cyclin D1 along with epithelial–mesenchymal transition (EMT)-related proteins and p-ERK and MMP2 in gastric cancer cells." (PMID 36769170, 2023). "The short-form recepteur d'origine nantais (sf-RON) was found to enhance glucose metabolism in gastric cancer by activating the β-catenin/SIX1 signaling axis, which promotes tumor cell proliferation, which indicated that sf-RON might serve as a promising therapeutic target for gastric cancer." (PMID 36750914, 2023).
colorectal cancer (13 papers, 2016 to 2024). A primary or metastatic malignant neoplasm that affects the colon or rectum. "Several studies have reported that SIX1 overexpression is frequently associated with poor patient prognosis in various malignancies, as colorectal cancer and glioma, however not in melanoma." (PMID 31069961, 2019). "Moreover, SIX1 and ezrin are significant independent prognostic factors in colorectal cancer, and ezrin expression is associated with colorectal cancer metastasis." (PMID 34771571, 2021). "The SIX1 transcription factor is important for the mesenchymal profile and drug resistance in various cancer types and is an independent prognostic marker in colorectal cancer." (PMID 34771571, 2021). "SIX1 is also up-regulated in colorectal cancer, correlates with poor overall survival and promotes cancer cell growth and metastasis in vitro and in vivo." (PMID 31438963, 2019). "The overexpression of SIX1 correlates with advanced clinicopathological characteristics and poor prognosis in esophageal cancer, colorectal cancer and hepatocellular carcinoma." (PMID 31438963, 2019). "SIX1 promotes EMT in colorectal cancer through ZEB1 activation." (PMID 35069900, 2022). "Indeed, SIX1 has been highlighted as an independent prognostic marker in colorectal cancer, and its profile can be used to stratify patients into different risk groups and guide individualized regimens." (PMID 27203207, 2016). "Overexpression of SIX1, another top-ranked CREB1-upregulated target, is an independent poor prognostic marker for stage I–III colorectal cancer." (PMID 34641874, 2021). "miR-30b blocks the translation of SIX1 by binding to its 3′-UTR, thereby delaying the progression of colorectal cancer." (PMID 27203207, 2016). "In addition, in colorectal cancer and pancreatic cancer, other studies have found that miR-30b targeted SIX homeobox 1 (SIX1) and snail, which were EMT (epithelial–mesenchymal transition)-promoting genes." (PMID 35291564, 2022). "In addition, SIX1 and SIX4 have been shown to upregulate PI3K/AKT signaling in osteosarcoma and colorectal cancer, respectively, possibly through the downregulation of PTEN to further suppress apoptosis." (PMID 34490256, 2021). "SIX1 could transcriptionally suppress the expression of miR-200 family and post-transcriptionally promote ZEB1 expression, consequently repressing E-cadherin expression and promoting epithelial-mesenchymal transition (EMT) in colorectal cancer." (PMID 31438963, 2019).
pancreatic cancer (13 papers, 2013 to 2025). "Pancreatic tumours with impaired expression of Six1 showed significantly delayed growth and displayed loss of the CD24+/CD44+ phenotype." (PMID 28388884, 2017). "We also demonstrate that the gene encoding cyclin D1 is a direct transcriptional target of Six1 in pancreatic cancer cells." (PMID 23527134, 2013). "We also show that the gene encoding cyclin D1 is a direct transcriptional target of Six1 in pancreatic cancer cells." (PMID 23527134, 2013). "The study of Ge W. showed, though, that NK cell’s functional impairment might be directly associated with lactate via sine oculis homeobox homolog 1 (SIX1)/lactate dehydrogenase A (LDHA) axis in pancreatic cancer." (PMID 40361394, 2025). "SIX1 expression was overexpressed in pancreatic cancer clinical samples, while NK cell co-culture with SIX-1 overexpressing pancreatic cancer cell lines resulted in downregulation of activation and cytotoxic markers in NK cells." (PMID 40361394, 2025). "For instance, SIX1 is upregulated in the cervical 21 and pancreatic cancers 22; MNX1 correlates with multiple tumours 23-25." (PMID 37779874, 2023). "SIX1 is up-regulated in pancreatic cancer tissues and promotes cell migration and invasion in vitro and growth in vivo." (PMID 31438963, 2019). "Overall, our results provide further evidence that Six1 co-promotes tumour progression in pancreatic cancer." (PMID 28388884, 2017). "Taken together, these results indicate that Six1 promotes cell proliferation of pancreatic cancer cells." (PMID 23527134, 2013). "To investigate the role of Six1 in pancreatic cancer development, we tested the expression of Six1 in 51 pancreatic ductal adenocarcinomas and 13 adjacent non-tumor pancreatic tissue samples using quantitative Real-time RT-PCR." (PMID 23527134, 2013). "The critical role of Six1 in the initiation and progression of numerous cancers impelled us to study the function of Six1 in pancreatic cancer." (PMID 23527134, 2013). "In agreement with our study, four independent datasets in ONCOMINE database showed that the expression of Six1 is upregulated in pancreatic cancer." (PMID 23527134, 2013). "In this study, we demonstrate that Six1 is overexpressed in pancreatic cancer and correlated with advanced tumor stage." (PMID 23527134, 2013). "To summarize, our study demonstrates that Six1 is overexpressed in pancreatic cancer, leading to an increase in cancer cell growth and cell cycle progression through upregulation of cyclin D1." (PMID 23527134, 2013). "It not only yields a better understanding of the role of Six1 in pancreatic cancer, but also paves the way for novel and powerful anticancer therapeutics." (PMID 23527134, 2013). "Secondly, our data demonstrated that Six1 expression significantly correlates with cyclin D1 in human pancreatic cancer." (PMID 23527134, 2013). "In this study, we found that cyclin D1 was required for Six1-induced cell proliferation and tumor growth in pancreatic cancer." (PMID 23527134, 2013). "Here we show that the relative expression of Six1 mRNA is increased in pancreatic cancer and correlated with advanced tumor stage." (PMID 23527134, 2013). "In vitro functional assays demonstrate that forced overexpression of Six1 significantly enhances the growth rate and proliferation ability of pancreatic cancer cells." (PMID 23527134, 2013). "In this study, we demonstrated that forced overexpression of Six1 enhanced the proliferation and colony formation of pancreatic cancer cells, while knockdown of endogenous Six1 significantly reduced the growth rate of these cells." (PMID 23527134, 2013). "In order to explore the functional role of Six1 in pancreatic cancer, we examined the effect of Six1 overexpression on the proliferation of both PANC-1 and MIA PaCa-2 cells." (PMID 23527134, 2013). "SIX1 was reported to inhibit tumor invasion and might be a novel therapeutic target in pancreatic cancer." (PMID 32065213, 2020).
pancreatic cancer (continued). "Taken together, these results suggest that Six1 may also promote cyclin D1 expression in human pancreatic cancer." (PMID 23527134, 2013). "Furthermore, we queried the ONCOMINE database to confirm gene expression levels of Six1 in pancreatic cancer." (PMID 23527134, 2013). "Our results complement the previous studies and further suggest that the upregulation of Six1 might contribute to pancreatic cancer tumorigenesis." (PMID 23527134, 2013). "Moreover, our in vivo xenograft tumorigenesis model also confirms that upregulation of Six1 increases the growth rate of pancreatic cancer in nude mice." (PMID 23527134, 2013). "To test whether Six1 is required for proliferation of pancreatic cancer cells, we silenced Six1 in both PANC-1 and MIA PaCa-2 cells using siRNA method." (PMID 23527134, 2013). "In addition, the alterations in Six1 expression become progressively worse with increasing stage of pancreatic cancer, suggesting its potential use as a new prognostic marker." (PMID 23527134, 2013). "To determine whether both Six1 and cyclin D1 are coordinately expressed in pancreatic cancer, we examined their protein expression in the xenograft tumors from PANC-1 cells stably transfected with either Six1 or control plasmids." (PMID 23527134, 2013). "However, the clinical significance of Six1 overexpression in pancreatic cancer tissues and the prognostic value of the data need to be confirmed by future studies." (PMID 23527134, 2013). "Therefore, targeting Six1 might be a novel promising therapeutic approach in patients with pancreatic cancer." (PMID 28388884, 2017). "Furthermore, Six1 promotes the growth of pancreatic cancer cells in a xenograft assay." (PMID 23527134, 2013). "Furthermore, we examined the expression of Six1 and cyclin D1 in three other independent pancreatic cancer microarray datasets and all of them showed a significant correlation between the two (GSE15471: r: 0.477, P = 0.0021; GSE32676: r: 0.372, P = 0.036; and GSE28735: r: 0.767, P<0.0001)." (PMID 23527134, 2013). "Therefore, targeting Six1 might be a novel therapeutic approach in patients with pancreatic cancer." (PMID 28388884, 2017). "SIX1 has been reported to increase CSC numbers in vitro and in vivo: SIX1 increased phenotypic and functional CSCs in breast, colorectal and esophageal cancer and phenotypic CSCs in pancreatic cancers." (PMID 38031089, 2023). "Our results showed that Six1 was overexpressed in pancreatic cancer in comparison to the adjacent non-tumor pancreas tissues." (PMID 23527134, 2013). "In four microarray expression studies, the expression of Six1 mRNA is significantly higher in pancreatic cancer tissues than in the adjacent non-tumor pancreatic tissues; the mRNA levels increase between 1.5- and 11.2-fold." (PMID 23527134, 2013). "However, the expression of Six1 in pancreatic cancer has not been examined in detail." (PMID 23527134, 2013). "However, the role of Six1 in pancreatic cancer is not clear." (PMID 23527134, 2013).